INS (insulin)
Diseases named in the same sentence as INS in open-access papers (continued):
Sharing a sentence is not in itself a finding about the gene and the disease.
tauopathy (21 papers, 2017 to 2025). Neurodegenerative disorders involving deposition of abnormal tau protein isoforms (tau proteins) in neurons and glial cells in the brain. "Tauopathy can directly inhibit glycolysis, drive mitochondrial dysfunction, lead to brain insulin resistance and cause disturbances in glutamate homeostasis." (PMID 35281504, 2022). "Clinical and preclinical studies revealed an association between impaired insulin signaling and tau pathology in AD and other tauopathies." (PMID 34512303, 2021). "Both clinical and preclinical studies have found an association between impaired insulin signaling and tau pathology in AD and other tauopathies." (PMID 34512303, 2021). "A previous study revealed GAS5 levels to be consistently reduced in human AD brain samples, and furthermore that depletion of GAS5 decreases insulin signaling in neurons and increases phosphorylated tau, which influences synaptic dysfunction in tauopathies." (PMID 39979805, 2025). "Following extended torpor, hibernators must rapidly recover from immobility, nutrient deprivation, insulin resistance, accumulated wastes and toxins, and tauopathy." (PMID 38979381, 2024). "Take AD for example: it can promote Aβ aggregation and simultaneously inhibit Aβ clearance, trigger synaptic dysfunction, disrupt the blood–brain barrier, exaggerate tauopathy‐mediated neurodegeneration, and dysregulate insulin signaling." (PMID 37700547, 2023). "Elsewhere, it has been observed that in cases of AD and several of the most prevalent human tauopathies, insulin accumulates as oligomers in hyperphosphorylated Tau-bearing neurons." (PMID 34576151, 2021). "Tau35 has deleterious effects on signaling pathways that mediate pathological changes and insulin resistance, suggesting a mechanism through which N-terminal cleavage of tau leads to the development and progression of tau pathology in human tauopathy." (PMID 30606258, 2019). "To investigate how insulin signaling impacts tau pathology, we utilized our well-established model of Tauopathy in which we expressed full-length wild type human Tau (2N4R) in Drosophila eyes using the pan-retinal GMR-GAL4 driver." (PMID 31427921, 2019). "In another study, hyperphosphorylated Tau-containing neurons from insoluble fractions of post-mortem AD and other tauopathies were shown to contain insulin accumulated as oligomers." (PMID 30804755, 2019). "Likewise, proteopathies, such as β-amyloidosis and tauopathy in AD, also purportedly induce an insulin-resistant–like state." (PMID 35798912, 2022). "Defective brain insulin signaling has been suggested as an early event in AD and other tauopathies but the mechanisms that link these diseases are largely unknown." (PMID 31427921, 2019). "However, it remains to be elucidated whether impaired insulin signaling, or Tau pathology comes first in AD pathogenesis and other tauopathies." (PMID 30804755, 2019). "Moreover, it has been demonstrated that tau hyperphosphorylation leads to an increase in uptake and intraneuronal accumulation of insulin as insoluble oligomeric aggregates in LOAD patients and in several tauopathies." (PMID 34577590, 2021). "Given the inter-dependence of these two pathways, suppressed insulin signaling may be the synergistic consequence of activation of both the UPR and mTORC1/S6K1 pathways in CHO-Tau35 cells and potentially also in human tauopathy brain." (PMID 30606258, 2019). "Hence, tau deletion is involved in the control of peripheral and brain insulin metabolism, the modulation of hippocampal BIR can contribute to cognitive function and hypothalamic BIR regulates metabolic alterations in LOAD patients and in tauopathies." (PMID 34577590, 2021). "Thus, in our Tauopathy model, the impact of hyperphosphorylated and aggregated tau on autophagic clearance in an insulin-resistant environment cannot be ruled out." (PMID 31427921, 2019).
tauopathy (continued). "Studies performed in post-mortem brains from patients with tauopathies including AD, Pick’s disease, corticobasal degeneration, and progressive supranuclear palsy, showed increases in phosphorylated IRS1 levels which, as we have already mentioned, is a specific marker of insulin resistance." (PMID 29382127, 2018). "Finally, recent data reported that insulin accumulates intraneuronally together with hyperphosphorylated TAU in LOAD and several other tauopathies suggesting that hyperphosphorylated TAU-bearing neurons is a causative factor involved in the brain insulin resistance observed in LOAD." (PMID 29382127, 2018).
hyperlipemia (20 papers, 2010 to 2024). "It is possible that hyperlipemia (in obese patients) causes also a superoxide-mediated activation of UCP-2 and thus a loss in insulin secretion (UCP-2 knockout mice maintain insulin secretion after long-term incubation with palmitic acid)." (PMID 39201524, 2024). "This can be explained by hepatic lipidosis inducing a decreased hepatic insulin clearance, or vice versa, an impaired glucose hepatic intake inducing hyperlipemia and hepatic lipidosis." (PMID 38396558, 2024). "Cytokines stimulating the hepatic production of C4 may also induce hyperlipemia and undermine insulin sensitivity." (PMID 35768780, 2022). "These last two situations could predispose horses to severe health problems such as equine metabolic syndrome, insulin dysregulation, hyperlipemia, and laminitis." (PMID 36288157, 2022). "Lipolysis, other than glycogenolysis and gluconeogenesis, is assumed to be stimulated by catecholamines and other catabolic hormones related to stress (insulin and cortisol) and is thus reported to affect glucose and lipid metabolism and provoke an exercise-induced transient hyperlipemia." (PMID 32085444, 2020). "Our study here shows that FcγRIIb knockdown and knockout increase the insulin-induced phosphorylation of AKT and FOXO1 in HepG2 and the animal model, suggesting that FcγRIIb inhibits insulin-induced activation of AKT and FOXO1, and in turn upregulates G6Pase and PEPCK in hyperlipemia in hepatocytes." (PMID 30261661, 2018). "However, according to this research and other animal experiment studies, the chronic sleep disturbance resulted in an attenuation of weight gain without hyperlipemia, it implied that the body weight and serum lipid cannot explain the insulin resistance after chronic sleep disturbance." (PMID 27738407, 2016).
mental disorder (20 papers, 2016 to 2025). A disease that has its basis in the disruption of mental process. "Our work might open up new directions for clinical and neuropsychopharmacological research by introducing insulin signalling as a possible mechanism underlying the multimorbidity of major mental disorders and somatic diseases." (PMID 35165256, 2022). "Higher levels of TG and insulin in patients with mental disorders could be caused by low NEAT in psychiatric patients." (PMID 26765475, 2016). "Curcumin has been found potential in regulating issues related to neurodegeneration and mental disorders and enhancing insulin sensitivity in insulin-resistant HepG2 cells by boosting PI3K-AKT-GSK3β signaling and inhibiting ERK/JNK phosphorylation." (PMID 41155319, 2025). "There was another incident, which involved another patient with mental disorders who came to collect insulin for his mother." (PMID 35525972, 2022). "In patients with mental disorders, serum TG and insulin were significantly higher (by 26% and 67%, respectively), and plasma BNP and baPWV were significantly lower (by 54% and 11.7%, respectively)." (PMID 26765475, 2016). "Third, medication provided to treat mental disorders can alter insulin sensitivity." (PMID 35729420, 2022). "Also in recent genetic studies examining pathways contributing to compulsivity-related mental disorders and traits, insulin signaling has been identified as an important mechanism involved." (PMID 36028833, 2022). "Another hypothesis is that glucose homeostasis may cause mental disorders, regardless of the body weight; for example, the group of Bendix M. confirmed that higher insulin and lower glucagon plasma levels, are associated with SB." (PMID 29880751, 2018). "The possibility of insulin use may be another reason induced the mental disorder of the proband." (PMID 28105082, 2017). "A Combination of insulin and non-insulin medication was mostly used by T2D patients with both cardiovascular diseases and mental disorders (T2D + CVD + AMD), and the use of insulin increased among this group in follow-up." (PMID 36352358, 2022). "A Combination of insulin and non-insulin medication was mostly used for the T2D patients who had both mental disorders and CVD." (PMID 36352358, 2022). "The rates of patients with positive screening for common mental disorders did not vary according to duration of use of insulin analogues, between patients aged < or ≥ 38 years (p = 0.87), or between type of protocol for insulin analogue provision (administrative or judicial)." (PMID 33905628, 2021).
non-alcoholic fatty liver (20 papers, 2014 to 2023). A benign form of fatty non-alcoholic fatty liver disease where the disease has not yet progressed to the inflammation of liver. "ApoC-III gene mutations and ApoC-III levels are also associated with the development of nonalcoholic fatty liver, hepatic insulin resistance, and T2DM." (PMID 30302116, 2018). "ALT is a representative biomarker for liver function and also considered an epidemiologic marker for non-alcoholic fatty liver because it is related to insulin sensitivity." (PMID 33564044, 2021). "Our study has indicated that daily oral administration of multiprobiotic to neonatal MSG-treated rats by 2-week courses led to significant reduce of total body and VAT weight with subsequent improvement in insulin sensitivity and prevention of non-alcoholic fatty liver (NAFLD) development." (PMID 25030027, 2014). "Outcomes from a lifestyle intervention trial involving insulin-sensitive and insulin-resistant adults with non-alcoholic fatty liver (NAFL) showed that LPC 16:0 was higher in the insulin-sensitive group and may serve as a biomarker for insulin sensitivity in individuals with NAFL." (PMID 37686719, 2023).
Stillbirth (20 papers, 2009 to 2025). Death of the fetus in utero after at least 22 weeks of gestation. "Furthermore, the elevated risk of macrosomia and stillbirth observed in our study reflects established physiological mechanisms such as insulin resistance and placental dysfunction, which are prevalent in obese pregnancies." (PMID 41220473, 2025). "When maternal obesity, smoking, chronic hypertension, antiphospholipid syndrome, type 2 diabetes, and insulin requirement are used in a prediction model risk calculator for stillbirth, it predicted stillbirths at 60—72% AUC at 75% sensitivity and close to 100% specificity." (PMID 36403017, 2022). "The risk of stillbirth and abortion or miscarriage during the index pregnancy might be indicative of women with poor blood glucose control and various endocrine system problems which affect the normal metabolism of insulin, which might then predispose women to recurrent or risk for GDM." (PMID 31402976, 2019). "Our primary outcome was a composite of stillbirth, spontaneous preterm birth or preterm premature rupture of membranes, and iatrogenic preterm birth or cesarean birth for fetal wellbeing concerns, occurring following the drop in insulin requirements." (PMID 41227133, 2025). "Findings revealed that individual components of AL, such as CRP, BMI, DBP, SBP, and HDL, and insulin during the first trimester were significantly associated with hypertensive disorders of pregnancy (OR: 2.5, 95% CI: 2.0–2.9) but not with preterm birth, small for gestational age, or stillbirth." (PMID 41586415, 2025). "Dietary adaptations and insulin for GDM, antepartum fetal monitoring for stillbirth, acetylsalicylic acid for pre-eclampsia, and progesterone for preterm delivery are a few examples of such therapies that have been proposed in high-risk populations." (PMID 39696496, 2024). "The majority of all perinatal deaths were stillbirths: eight of 11 in the OGLA alone group and five of seven in the OGLA to insulin group." (PMID 21501437, 2011). "Certain first-trimester AL biomarkers, notably CRP, BMI, DBP, SBP, HDL, and insulin, are significantly associated with HDP, but not with outcomes like preterm birth, SGA, or stillbirth." (PMID 41586415, 2025). "There were two stillbirths reported in the group of pregestational diabetics using NPH insulin and none in the glargine utilizing group (p-value=0.028)." (PMID 21501437, 2011).
thyroid nodule (20 papers, 2012 to 2026). A small circumscribed mass in the THYROID GLAND that can be of neoplastic growth or non-neoplastic abnormality. "Previous studies and the present work argue for focusing future research on the potential role of waist circumference-associated insulin resistance in the formation of thyroid nodules." (PMID 29374470, 2018). "According to our results, TSH was inversely correlated with the risk for thyroid nodules, and this could also be caused by the insulin pathway." (PMID 24244604, 2013). "Both elevated TSH concentrations and impaired insulin sensitivity increase the risk of thyroid enlargement and nodular thyroid hyperplasia, while metformin treatment was found to decrease the prevalence and incidence of goiter and to reduce thyroid nodule size." (PMID 40872540, 2025). "Therefore, high circulating insulin levels may increase thyroid proliferation and cause thyroid nodule formation and an increase in TV." (PMID 27901182, 2017). "Existing retrospective studies support a significant link between insulin resistance and thyroid nodules." (PMID 39444449, 2024). "The described effect of myo-Ins and IP6 in anticancer prevention, by inhibiting PI3K and the downregulation of Akt activity and reducing insulin resistance, proposes myo-Ins as a protective factor for the malignant transformation of thyroid nodules and metastatic spread development." (PMID 39199391, 2024). "Individuals with impaired fasting glucose may exhibit elevated insulin levels, potentially leading to the proliferation of thyroid cells and the formation of thyroid nodules." (PMID 38628585, 2024). "Conversely, elevated insulin may affect the prevalence and size of thyroid nodules and thyroid volume, revealing a bidirectional interconnection between the two conditions." (PMID 35740085, 2022). "It was supposed that the role of insulin in promoting the formation of thyroid nodule may be partially mediated by the proliferation effective of IGF-1." (PMID 34550096, 2021). "Taken together, these data suggest that metformin might play a role in prevention and treatment of thyroid nodules and cancer in insulin resistant patients." (PMID 29184536, 2017). "This suggests a potential approach for preventing and managing thyroid nodules and related diseases: could controlling metabolic indicators to reduce insulin resistance levels effectively lower the occurrence and progression of endocrine disorders, including thyroid conditions?" (PMID 41409611, 2025). "These considerations may point to a key role of insulin resistance in formation of thyroid nodules." (PMID 29374470, 2018). "Similarly, some studies reported a coexistence between insulin resistance and thyroid nodules." (PMID 22319523, 2012). "Due to high homology of IGF-1 and IGF-2 to each other and to insulin, and involvement in cell proliferation, IGF-2 could also play a role in the development of thyroid nodules and/or thyromegaly." (PMID 35158824, 2022). "We detected higher fasting insulin and HOMA-IR values in patients with thyroid nodules." (PMID 28400351, 2017). "However, it is possible to speculate that insulin may stimulate vascular endothelial growth factor (VEGF) expression and promote proliferation of vascular endothelial cells in thyroid nodules and tumors, as shown in other contexts." (PMID 29184536, 2017). "Participants with thyroid nodules were older and had higher fasting glucose, fasting insulin, HOMA-IR, and BMI compared with those without thyroid nodules." (PMID 28400351, 2017). "Participants with thyroid nodules were older and had higher fasting glucose, BMI, fasting insulin, and HOMA-IR values compared with those without thyroid nodules (p<.05)." (PMID 28400351, 2017). "Furthermore, participants with thyroid nodules were older with higher fasting blood glucose, BMI, fasting insulin, and HOMA-IR values than participants without thyroid nodules, indicating an increased incidence of nodular goiter in PCOS patients." (PMID 37867519, 2023).
thyroid nodule (continued). "Additionally, participants with thyroid nodules were older and had higher BMI, fasting glucose, fasting insulin, and HOMA-IR compared with those without thyroid nodules." (PMID 28400351, 2017).